FOXP3 (forkhead box P3)
Diseases named in the same sentence as FOXP3 in open-access papers (continued):
Sharing a sentence is not in itself a finding about the gene and the disease.
IPEX syndrome (continued). "Indeed, in mice, invalidating mutations in the Foxp3 gene or specific ablation of Foxp3+ T cells lead to the development of a fatal lymphoproliferative disorder and humans with mutations in the FOXP3 gene suffer from the lethal immune-dysregulation polyendocrinopathy enteropathy X linked syndrome." (PMID 28167946, 2017). "In mice with IPEX syndrome, the depletion of E251 impaired the heterodimerization of FOXP3 with FOXP1, thus suggesting a role for such heterodimerization in suppressive immune activity." (PMID 27965764, 2015). "However, compared with other monogenic blood diseases, restoration of FOXP3 in IPEX syndrome presents several challenges." (PMID 39372653, 2024). "In IPEX syndrome (immune dysregulation, polyendocrinopathy, enteropathy X-linked syndrome) (OMIM #304790), mutations in the FOXP3 gene which encodes for a transcription factor lead to a rare genetic autoimmune disease which manifests with NDM, enteropathy, and polyendocrinopathy." (PMID 39408828, 2024). "Treg development and function is dependent on the forkhead box protein-3 (FOXP3) transcription factor, deficiency of which abrogates Treg development and causes IPEX syndrome with absent or dysfunctional Tregs." (PMID 38022498, 2023). "From the study by Ochs and Torgerson on 100 patients with a phenotype corresponding to IPEX syndrome, nearly half of them did not have a mutation in the FOXP3 transcription factor gene." (PMID 35207219, 2022). "IPEX syndrome (MIM #304790) also known as immune dysregulation, polyendocrinopathy, enteropathy, X-linked is a monogenic inborn error of immunity due to loss-of-function mutations in the forkhead box 3 (FOXP3) gene." (PMID 36503523, 2022). "Peripheral FOXP3 expression was normal (CD127−/CD4+/CD25+/FOXP3+—396 cells—63%) and a pathogenic mutation in FOXP3 gene (c.1150G>A; p.Ala384Thr), confirmed the diagnosis of IPEX syndrome." (PMID 36503523, 2022). "Accumulated data also suggest that IPEX syndrome may be a consequence of alternatively spliced FOXP3." (PMID 34768829, 2021). "Half of the patients with typical clinical symptoms of IPEX syndrome present with no FOXP3 mutation, but have other gene mutations." (PMID 33668198, 2021). "Moreover, they formally prove the need of preserving endogenous FOXP3 regulation for an HSC-based gene therapy approach for IPEX syndrome." (PMID 29150659, 2017). "This conclusion arose from the overwhelming evidence that systemic autoimmunity ensued in the absence of Tregs, as in day 3 thymectomy mouse models, Foxp3 mutation in mice (scurfy) and humans (IPEX syndrome), or even in Foxp3 conditional KO mouse models." (PMID 27242798, 2016). "In the patients with IPEX syndrome, the lack of the forkhead box protein 3 in lymphoid tissues (thymus, spleen, and lymph nodes), encoded by FOXP3 gene at Xp11.23-Xq13.3, leads to impaired development and suppressed function of CD4+CD25+ T-reg." (PMID 24982679, 2014). "A missense loss-of-function mutation within the FOXP3 locus can result in self-reactive lymphocytes that can lead to the development of severe autoimmunity in scurfy mice or cause a rare, but severe, disease IPEX (immune dysregulation, polyendocrinopathy, enteropathy, X-linked) syndrome in humans." (PMID 36675037, 2023). "The correlation of FOXP3 genotype and clinical phenotype in IPEX syndrome is not straightforward because the same mutation in different individuals may result in different clinical presentations." (PMID 36091011, 2022). "The transcription factor FOXP3 is critical for regulatory T cell function and the maintenance of immune tolerance; allergists should be familiar with IPEX syndrome, as patients may initially present with dermatitis, and some are diagnosed with allergic diseases before the condition is recognized." (PMID 35273610, 2022). "Thus, in IPEX syndrome, FOXP3 mutations do not hamper the development of tTreg precursors and the emergence of Tregs in the periphery." (PMID 33692972, 2021).
IPEX syndrome (continued). "In scurfy mice, a mouse model of human IPEX syndrome, treatment with TGFβ-differentiated FOXP3+ T cells from wt mice or autologous transplantation of hematopoietic stem cell containing a lentiviral vector for FOXP3 overexpression has been shown to sufficiently prevent skin inflammation." (PMID 31909202, 2020). "This case illustrates that a classical pathogenic mutation in FOXP3 can lead to a clinical phenotype where the diagnosis of IPEX syndrome was never considered because of the lack of diabetes and the presence of only mild eczema, in addition to the normal Treg cell numbers and FOXP3 expression." (PMID 28289675, 2017). "Additionally, the rare disorder of the immune system, immune dysregulation, polyendocrinopathy, enteropathy X-linked (IPEX) syndrome, is caused by mutations in the FOXP3 gene that result in defective development of CD4+ CD25+ Treg; children with IPEX syndrome demonstrate high levels of serum IgE." (PMID 23226205, 2012). "If CD4+CD25+FOXP3+ cells cannot actively suppress effector T cells, how can one account for the phenotypes of the scurfy mouse, and those individuals suffering from the XLAAD/IPEX syndrome?" (PMID 18324310, 2008). "Rapamycin provides benefit in IPEX syndrome by partially restoring Treg function independent of FOXP3 expression or Treg frequency." (PMID 37727514, 2023). "A recent study shows that the lack of exon 2 of FOXP3 in mice and patients with IPEX syndrome leads to severe immune disorders." (PMID 38259469, 2023). "It has also been demonstrated that patients with IPEX syndrome who have missense mutations and deletions in splicing sites do not have Treg CD4+CD25+Foxp3+ lymphocytes and have a more severe form of the disease." (PMID 35207219, 2022). "IPEX syndrome results in spontaneous inflammation of many organs, yet IPEX patients most frequently suffer from severe gastrointestinal disorders and food allergies, emphasizing the key role of Foxp3+ Treg cells in establishing tolerance within the intestine." (PMID 33193456, 2020). "Although IPEX syndrome has not been reported, carriers display a bimodal FOXP3 expression within the CD4+CD25+CD127low T-cell population for FOXP3 mutations that do not affect Treg-cell development (e.g., c.1150G>A)." (PMID 33194927, 2020). "Indeed, a registered clinical trial (NCT05241444), which is still recruiting patients, aims to test in 30 participants with IPEX syndrome the infusion of autologous CD4+ T cells, which have undergone lentiviral-mediated gene transfer of the healthy human FOXP3 gene." (PMID 41226379, 2025). "In individuals with IPEX syndrome, functional Tregs are largely absent, and one of the most typical Treg markers, intracellular antibody staining of FOXP3, may no longer work." (PMID 36600150, 2023). "A decreased frequency of FOXP3+ Tregs has been observed in the peripheral blood of some, but not all, STAT3 GOF patients, and taken together with the overlapping clinical features in STAT3 GOF and IPEX syndrome, it has been suggested that this disease falls within the spectrum of Tregopathies." (PMID 36136607, 2022). "This, together with the fact that FOXP3 is not expressed by PM (unpublished observation), indicates that the recovery of a functional Treg compartment limits the peritoneal inflammation in experimental model of IPEX syndrome via functional reprogramming of PM and peritoneal T cells." (PMID 30429849, 2018).
lupus (131 papers, 2007 to 2025). "Conversely, in a related human context, low miR-10a in lupus Tregs was associated with reduced FOXP3 acetylation and unstable Tregs." (PMID 41376628, 2025). "L. delbrueckii and L. rhamnosus increase regulatory T cell differentiation and regulatory potential in pristane-induced lupus mice, associated with enhanced FOXP3 expression and reduced inflammation." (PMID 40534849, 2025). "miR-31 targets forkhead-box p3 (Foxp3); therefore, miR-31 upregulation is associated with Treg dysfunction in lupus." (PMID 39558370, 2024). "The FoxP3/rs3761548 polymorphisms the AA genotype was also reported to be a risk factor for several diseases, including MS, acute coronary syndrome, systemic lupus erythematosus, vitiligo, allergy and thyroid cancer." (PMID 37904681, 2023). "Reverse genetic approaches have identified several genes that control Treg cell number, stability and/or functions through Foxp3 expression, and whose deficiency or overexpression lead to autoimmunity or lupus-like manifestations." (PMID 35693798, 2022). "Studies reported the association of FOXP3 variants/polymorphs with various disorders such as systemic lupus erythematosus (SLE), atherosclerosis, autoimmune thyroid disease (AITDS), and PE." (PMID 36554576, 2022). "mTOR inhibits the development of CD4+CD25+forkhead box P3(FoxP3)+ regulatory T cells (Tregs), which are deficient in lupus patients." (PMID 34239993, 2021). "For instance, Foxp3 polymorphisms in promoter, exon, intron or Poly A region of Foxp3 gene locus have been detected in rheumatoid arthritis (RA), systemic lupus erythematosus (SLE), type 1 diabetes (T1D) and even in IPEX itself." (PMID 33519807, 2020). "Recently, it was reported that IL-17-producing FOXP3+ T cells were associated with pathogenicity in a lupus model mouse in a RORγt-dependent manner." (PMID 31354747, 2019). "Other studies found Foxp3 -6054 and -3279 polymorphisms were associated with habitual abortion, systemic lupus erythematosus and allergic rhinitis." (PMID 23560055, 2013). "It has been reported that there are associations between Foxp3 gene polymorphisms and autoimmune diseases, such as systemic lupus erythematosus (SLE), autoimmune thyroid diseases (AITDs), type I diabetes (TID), and allergic rhinitis." (PMID 21876709, 2012). "The FOXP3 gene variants, including rs2280883 and rs3761548, have been extensively studied in immune-mediated diseases such as systemic sclerosis, rheumatoid arthritis, Graves’ disease, and systemic lupus erythematosus." (PMID 40076417, 2025). "Similarly, the low expression of CTLA4 in Foxp3+CD25+CD4+ Tregs has been negatively associated with disease activity in patients with systemic lupus erythematosus." (PMID 39284778, 2024). "Therefore, to explore the possible effects of single-nucleotide polymorphisms, here, we evaluated the association of IVS9+459/rs2280883 (T>C) and −2383/rs3761549 (C>T) Foxp3 polymorphisms with systemic lupus erythematosus." (PMID 37998578, 2023). "Additionally, we have previously shown that the peritoneal injection of SOCS1-KIR into a rodent model of SOCS1 genetic deficiency, or spontaneous lupus model, decreased circulating memory T cells and increased Foxp3 high T lymphocytes." (PMID 35505065, 2022). "The aim of this study was to evaluate the association of rs2232365 (-924 G > A) and rs3761548 (-3279 C > A) FOXP3 variants with systemic lupus erythematosus (SLE) susceptibility, TGF-β1 plasma levels, autoantibodies, and LN nephritis, and SLE disease activity index (SLEDAI)." (PMID 33686190, 2021). "Furthermore, decreased renal levels of Foxp3 and IL-10 are associated with glomerulonephritis in pristane-induced lupus mice." (PMID 31488076, 2019). "The upregulation of miR-31 in T cells may correlate with the deficiency of Treg cell development/function in lupus since miR-31 targets Foxp3, a critical transcription factor for Treg cell development and function." (PMID 21170274, 2010).
lupus (continued). "For instance, total glucosides of paeony promote the generation of Tregs by inducing Foxp3 expression through reducing the DNA methylation level of the Foxp3 promoter in lupus CD4 T cells." (PMID 41458964, 2025). "Probiotics such as L. delbrueckii, L. rhamnosus, L. reuteri, and L. acidophilus induce CD4+CD25+Foxp3+ Tregs and suppress Th17 cells in lupus models via metabolite-mediated signaling pathways." (PMID 40534849, 2025). "There has already been considerable research devoted to developing immunotherapies which leverage FoxP3+ Tregs in the management of type I diabetes mellitus, systemic lupus erythematosus, and Crohn’s disease." (PMID 39975555, 2025). "This confirms that CD4+FoxP3+ Tregs derived from lupus-prone mice remained functionally intact and served as a physiologically relevant inhibitor of disease progression." (PMID 39000278, 2024). "TGP causes down-regulated Foxp3 promoter methylation levels, thus increasing the expression of Foxp3 in lupus CD4+ T cells." (PMID 37511964, 2023). "Of interest, Dex-NPs, but not dexamethasone, mediated the expansion of CD3+CD4+Foxp3+ Tregs and CD3+CD4+Foxp3+CD25+ activated Tregs in Fcgr2b-/- lupus-prone mice." (PMID 37176021, 2023). "In MRL/lpr mice, administration of the artemisinin analog SM934 ameliorated lupus development and suppressed serum levels of IFNγ but increased the expression of Foxp3 in Treg cells." (PMID 38164134, 2023). "Consistent with the high therapeutic potential of CD4+Lrig1+ T cells in IBD and lupus animal models, the higher expression of the genes involved in functions of Treg cells or induced by Foxp3 was observed in CD4+Lrig1+ T cells than CD4+Lrig1− T cells." (PMID 37666819, 2023). "Increased levels of Foxp3 mRNA have also been reported in urine from patients with active LN compared to patients with inactive lupus and healthy controls." (PMID 37368057, 2023). "Injection of the poly(lactic-co-glycolic acid) nanoparticle encapsulating TGF-β into lupus mice induced expansion of CD4+Foxp3+ Treg cells and CD8+Foxp3+ Treg cells and suppression of anti-dsDNA antibody and reduced renal disease." (PMID 38164134, 2023). "Increased levels of mir-34a, the second miRNA mostly upregulated in our miRNA-seq, have been described as an inductor of Th17 response by targeting FOXP3 in rheumatoid arthritis and systemic lupus erythematosus patients." (PMID 35370692, 2022). "Newer studies revealed that CD8+ Foxp3+ Tc regulatory cells suppressed effector T cell proliferation and autoantibody production by lupus B cells in vitro in a Foxp3- and PD1-dependent manner." (PMID 35055071, 2022). "In humans, CD8+Foxp3+ Tregs are detected in some patients with rheumatoid arthritis (RA), systemic lupus erythematosus (SLE), Epstein-Barr virus (EBV) infections, patients with prostate cancer and allogeneic stem cell transplantation." (PMID 34831195, 2021). "In the present study, we evaluated the expression of FoxP3 in pCons-tolerized B cells of lupus (BWF1 mice) compared with naïve B cells." (PMID 34093553, 2021). "To evaluate this, we correlated CD38 expression in T-cells with FoxP3 expression and immunosuppressive markers in lupus-prone mice." (PMID 34769406, 2021). "Studies in lupus-prone New Zealand Black × New Zealand White (NZB/W) F1 mice revealed that the ratio of CD4+ Foxp3+ Tregs to CD4+ Foxp3− conventional T cells declined in lymphoid organs of these animals." (PMID 33496881, 2021). "In mice CD8+ Tregs expressing Foxp3 are reported in lupus-prone mice, allogeneic stem cell and bone marrow transplantation." (PMID 34831195, 2021). "We found that lupus patients exhibited significantly reduced percentages of CD4+FoxP3+ (p < 0.0041) and CD8+FoxP3+ T cells (p < 0.0102) when compared to healthy controls." (PMID 33746959, 2021). "The percentage of FOXP3+Helios+ Treg cells positively correlates with the activity of the disease in systemic lupus erythematosus." (PMID 33562037, 2021).
lupus (continued). "The proportion of Foxp3+ cells in CD4+IL-17A+ cells was significantly greater in patients with lupus than in those with IgA nephropathy." (PMID 32317002, 2020). "We cannot exclude the possibility that high-salt intake affects the functional activity of CD4+ Foxp3+ Treg cells in our lupus model." (PMID 32296043, 2020). "A similar increase in Foxp3+ Treg cells in models of inflammatory bowel disease and lupus was observed." (PMID 32516999, 2020). "Baicalin and ex vivo expanded Foxp3+ regulatory T cells are promising therapeutics for the treatment of lupus." (PMID 30760702, 2019). "Nineteen probes for 16 lupus-relevant genes (Abca1, Apobec3, Ccr7, Ceacam3, Ets1, Foxp3, Hdac1, Ifng, Irf9, Itgam, Jhdm1d, Mmp9, Oscar, Slc4a1, Tbx21, and Tlr7) were identified from the database of male murine spleen." (PMID 30246031, 2018). "It has been demonstrated in lupus-prone mice that IL-6 produced by DCs inhibits Tregs, because Foxp3+ Treg cells lose Foxp3 expression and undergo conversion into Th17 cells under the effect of IL-6." (PMID 27852285, 2016). "FOXP3-expressing CD8+ T cells proved vital for CD4+CD25+ Tregs induced by a tolerogenic peptide to suppress murine lupus." (PMID 27887663, 2016). "Surprisingly, other researchers have reported increased percentages of CD4+ FOXP3+ in lupus and found that this result correlated with disease activity." (PMID 27887663, 2016). "Reduced levels of forkhead box P3 (FoxP3) in CD4+ Tregs in patients with active lupus are generally believed to be the reason why these patients have less Tregs-suppressive activity than their counterparts with inactive disease." (PMID 24864268, 2014). "Foxp3-expressing CD8+ T proved vital for CD4+CD25+ Treg cells induced by a tolerogenic peptide to suppress murine lupus." (PMID 24475019, 2014). "Recently, a study showed that the Foxp3 gene, which acts as the master regulator of the development of regulatory T-cells, expression level is decreased in lupus patients and further suggested promoter DNA methylation as a possible mechanism." (PMID 23054340, 2013). "The status of CD4+ CD25+ FOXP3+ regulatory T cells (Tregs) in lupus has been examined by numerous studies." (PMID 21708033, 2011). "In B/W mice with active lupus, the frequency of natural Tregs, as measured by Foxp3+ expression, was 96±2% in the cells identified by CD4+CD25+CD62LHI expression." (PMID 19551149, 2009). "Foxp3 expression in CD8+ T cells has also been reported in another immune tolerance model in lupus-prone mice." (PMID 17653037, 2007). "FOXP3 expression has been described in tumour infiltrating Tregs in epithelial solid tumours such as pancreatic adenocarcinoma, in glioma cells and in Bregs present in systemic lupus erythematosus (SLE)." (PMID 36973425, 2023). "The incidence and course of systemic lupus erythematosus (SLE) differ between the sexes, with a nine-fold higher incidence in women linked to the influence of estrogen on epigenetic, immune and genetic factors (X-linked genes such as Foxp3, TNF and Tlr7)." (PMID 35203537, 2022). "Scrufy mice do not produce Treg cells due to a mutation in Foxp3, causing them to develop a severe inflammatory disease with autoimmune components, including lupus-like manifestations." (PMID 35693798, 2022). "Since lupus is a gender-biased disease with a female to male ratio of 9:1, we determined whether FoxP3 expression in healthy male and female individuals varies in their regulatory T cell compartments." (PMID 33746959, 2021). "When the CD4+ T cells from lupus mice were cultured with PD-L1 positive MDSCs from lupus and/or control mice, only PD-L1 positive MDSCs obtained from control mice markedly inhibited proinflammatory Th1, Th17 cells and reciprocally induced Foxp3+ Treg cells." (PMID 33986739, 2021). "Because Tfr cells are derived from Treg cells, we speculated that Baicalin might also promote part of Foxp3+ Tfr cell differentiation and that these mixed Foxp3+ cells might be used to treat lupus." (PMID 30760702, 2019).